APP (amyloid beta precursor protein)
Diseases named in the same sentence as APP in open-access papers (continued):
Sharing a sentence is not in itself a finding about the gene and the disease.
familial Alzheimer disease (continued). "The genetic alterations in APP and PS1 (and PS2) that cause early onset familial Alzheimer's disease (AD) are well characterized, as are the consequences that disease-linked mutations in these proteins have on the endoproteolytic processing of APP." (PMID 18776935, 2008). "Finally, we find that rBMECs expressing the familial Alzheimer disease (fAD) mutation APP V717I show decreased barrier integrity and upregulation of inflammatory markers." (PMID 41287966, 2026). "Mutations in the amyloid precursor protein (APP) gene cause familial Alzheimer’s disease." (PMID 37299526, 2023). "And the Swedish mutation is familial Alzheimer’s disease (FAD) associated with the APP mutation." (PMID 38130871, 2023). "The first such peptide, humanin, was identified more than 20 years ago in an unbiased functional screen for clones that protect neuronal cells from death induced by amyloid precursor protein (APP) mutants, which are associated with early-onset familial Alzheimer’s disease." (PMID 36381197, 2022). "In familial Alzheimer’s disease, a mutation in APP can result in defective neurite extension." (PMID 34445251, 2021). "Many APP mutations cause early-onset Familial Alzheimer’s disease (FAD)." (PMID 33370284, 2020). "However, rare forms of familial Alzheimer’s disease are associated with mutations in APP that increase toxic amyloidogenic cleavage of APP and produce amyloid beta (Aβ) at the expense of sAPPα and other non-amyloidogenic fragments." (PMID 28852095, 2017). "The E693Δ (Osaka) mutation in APP is linked to familial Alzheimer’s disease." (PMID 28760161, 2017). "APP (Amyloid Beta (A4) Precursor) gene encodes specific kind of cell surface receptor and transmembrane precursor protein, which are amyloid beta proteins and it is known as being genetically linked to familial Alzheimer’s disease." (PMID 25885114, 2015). "Moreover, mice with over-expression of APP and mutation of presenilin (a risk factor for familial Alzheimer's disease) have increased production of amyloid-β protein and display enhanced territorial aggression when compared to wildtypes." (PMID 19997634, 2009). "APP mutations mapping to exons 16 and 17 favor plaque accumulation and cause Familial Alzheimer Disease (FAD)." (PMID 33370284, 2020). "Mutations in APP and presenilin (PS1), a protein involved in APP to Aβ proteolysis, cause rare autosomal dominant forms of familial Alzheimer disease (FAD)." (PMID 21087849, 2011). "For example, amyloid aggregation followed by the hyperphosphorylation of tau protein was reproduced in organoids from the iPSCs of patients with familial Alzheimer’s disease with APP duplication." (PMID 40426657, 2025). "Subsequent research analyzed APP duplication (APPDp), a condition also correlated with early-onset, familial Alzheimer’s disease." (PMID 40426657, 2025). "Mutations in the APP, PSEN1, and PSEN2 genes trigger Familial Alzheimer’s Disease (FAD), also known as early-onset AD, which accounts for about 5%–10% of all AD patients." (PMID 40933041, 2025). "Exons 7, 8, and 15 are subject to alternative splicing, and duplications or triplications of the APP gene can result in familial Alzheimer’s disease (fAD)." (PMID 40725212, 2025). "For example, in familial Alzheimer’s disease (FAD), the allele-specific silencing of pathogenic APP Swedish mutation (APPswe), which results in excess Aβ production, is a valuable weapon in the therapeutic arsenal against FAD." (PMID 38972974, 2024). "Inherited forms of AD (familial Alzheimer’s disease, FAD) are caused by autosomal dominant mutations in the amyloid precursor protein (APP) and presenilin (PSEN1 and PSEN2) genes." (PMID 38987603, 2024). "Mutations in amyloid precursor protein (APP) and preselinins are associated with familial Alzheimer’s disease (fAD), which constitutes around 1% of AD cases, and are the cause of overproduction of amyloid β (Aβ) peptides." (PMID 38003628, 2023).
familial Alzheimer disease (continued). "Both amyloid precursor protein (APP) and presenilin (PSEN) gene mutations are associated with familial Alzheimer’s disease (FAD) and with the early onset of the disease." (PMID 36902234, 2023). "The striking discoveries, which moved the amyloid theory forward, are the linkage of the gene mutations in APP and presenilin, the catalytic core of γ-secretase complex (PSEN1 and PSEN2) to Familial Alzheimer’s disease (FAD)." (PMID 35865745, 2022). "Multiplications of the gene encoding the Aβ precursor protein (APP), as well as mutations in APP and the presenilin genes (PSEN1 and PSEN2), cause familial Alzheimer’s disease with abundant Aβ deposits and tau inclusions." (PMID 36635241, 2022). "Consistently, the lymphoblastoid cell line established from familial Alzheimer's disease (FAD) expresses higher APP than control patients." (PMID 34725916, 2021). "Mutations in amyloid precursor protein (APP) and presenilin 1 and 2 (PSEN1/2) cause familial Alzheimer’s disease (fAD)." (PMID 33440141, 2021). "The study identified clones that protected against neuronal cell death induced by neurotoxic amyloid-β peptides and by mutants of FAD (Familial Alzheimer’s Disease) genes, namely APP (Amyloid Precursor Protein), PS1 (Presenilin 1), and PS2 (Presenilin 2)." (PMID 32365540, 2020). "One is hereditary, known as familial Alzheimer’s disease (FAD), which is caused by mutations in the APP, presenilin 1 or presenilin 2 genes." (PMID 33218200, 2020). "Mutations of three causative genes, namely presenilin 1 (PSEN1), presenilin 2 (PSEN2), and amyloid precursor protein (APP), have been identified as the major causes of early‐onset familial Alzheimer's disease (EOFAD)." (PMID 32767553, 2020). "APP and PS1 gene mutations affect frontostriatal circuits in a different manner in familial Alzheimer’s disease; disease progression primarily affects the structure of hippocampus-PCC circuit." (PMID 31937364, 2020). "Genetic mutation related to both metabolism and expression of amyloid precursor protein (APP) are considered to be important for diagnosis of familial Alzheimer's disease." (PMID 31114535, 2019). "In patients with familial Alzheimer’s disease (FAD), mutations in the APP gene, PSEN1 gene, and PSEN2 gene were found." (PMID 31509519, 2019). "Mutations in the human genes PRESENILIN1 (PSEN1), PRESENILIN2 (PSEN2) and AMYLOID BETA A4 PRECURSOR PROTEIN (APP) have been identified in familial Alzheimer’s disease (AD)." (PMID 28636676, 2017). "The peptide was also shown to confer neuroprotection against an array of familial Alzheimer's disease (FAD) genes including presenilin 1, presenilin 2, and mutated APP." (PMID 28814984, 2017). "Several studies of mouse lines representing familial Alzheimer disease, mostly overexpression of APP, showed increased hippocampal neurogenesis." (PMID 27891071, 2016). "While gene mutations in the amyloid precursor protein (APP) and the presenilins lead to an accumulation of the amyloid β-peptide (Aβ) in the brain causing neurodegeneration and familial Alzheimer's disease (AD), over 95% of all AD cases are sporadic." (PMID 26617481, 2015). "Mutations in the genes of amyloid precursor protein (APP) and presenilins (PS1, PS2) increase the production of Aβ and cause familial Alzheimer’s disease." (PMID 26382037, 2015). "Genetic linkage analysis of familial Alzheimer’s disease (FAD) identified amyloid precursor protein (APP) and presenilins i.e. PSEN1 and PSEN2 as the causative genes in FAD." (PMID 25140287, 2014). "Pathogenic mutations in the three known genes – the amyloid precursor protein (APP), presenilin 1 (PSEN1), presenilin 2 (PSEN2) – are known to cause familial Alzheimer's disease (AD) and tend to be associated with early-onset AD." (PMID 25333068, 2014). "Amyloid precursor protein gene (APP) duplications have been identified in screens of selected probands with early onset familial Alzheimer's disease (FAD)." (PMID 21193246, 2012).
familial Alzheimer disease (continued). "Monogenic forms represent the infrequent, presenile or early-onset familial Alzheimer's disease (FAD), which is usually characterized by autosomal dominant point mutations of the genes of APP or the presenilin sub-domains of γ-secretase." (PMID 23211425, 2012). "Mutations in two PS genes, PS1 and PS2, cause familial Alzheimer disease (FAD) and elevate levels of the longer form of amyloid β-peptide (Aβ), which is derived from amyloid precursor protein (APP)." (PMID 19137062, 2009). "Early onset forms of Familial Alzheimer’s disease (FAD) typically present before the age of 65 and as early as 30 years of age and have been linked to mutations in APP, PS-1 and PS-2." (PMID 19578515, 2008). "Familial Alzheimer’s disease (FAD) is an inherited neurodegenerative disorder caused by autosomal-dominant mutations in the presenilin-1 (PSEN1), presenilin-2 (PSEN2), and amyloid-β precursor protein (APP) genes." (PMID 39754192, 2025). "Among the cases in this group, familial Alzheimer’s disease (FAD) accounts for approximately 80% and is triggered by mutations in three primary genes: Presenilin-1 (PSEN1), Presenilin-2 (PSEN2), and the amyloid precursor protein (APP) gene." (PMID 38338859, 2024). "Furthermore, the lack of tau expression has been reported to protect against excitotoxicity and prevent memory deficits in mice expressing mutant amyloid precursor protein (APP) identified in familial Alzheimer disease." (PMID 38844706, 2024). "Meanwhile, mutations in three different genes on chromosomes 1, 14, and 21 were reported to result in autosomal dominant forms of familial Alzheimer’s disease, that is24, the APP gene on chromosome 21, the PS1 gene on chromosome 14, and the PS2 gene onchromosome 123,25." (PMID 37100862, 2023). "Together, our results indicate that tubulin retyrosination is affected in sporadic and familial Alzheimer’s disease and that inhibition of microtubule dynamics observed in mutant APP human neurons is consistent with a disrupted tubulin tyrosination/detyrosination cycle." (PMID 35148384, 2022). "Mutations of APP and PS1/2 are usually found in early onset familial Alzheimer’s disease (FAD)." (PMID 34440599, 2021). "Mutations in APP and PSEN1/2 that cause familial Alzheimer’s disease (fAD) are believed to alter this interaction, increasing the relative proportion of aggregation-prone Aβ species, and forming the basis of the amyloid cascade hypothesis." (PMID 32395715, 2019). "Investigation of wild-type γ-secretase with six familial Alzheimer’s disease (FAD) mutants in PS1 and five FAD mutants in the Aβ peptide segment of the APP revealed that all mutations were associated with decreased γ-secretase activity and a reduced age of disease onset and death." (PMID 29857474, 2018). "These aberrant PS-1 processing steps in HPRT-deficiency LND may provide useful clues to previously unsuspected purinergic contributions to defective processing of APP as found in familial Alzheimer's disease." (PMID 21305049, 2011). "Usually, transgenic mice carrying multiple familial Alzheimer’s disease (FAD) mutations, such as APPswe/PSEN1ΔE9 (APP/PS1), 5xFAD and in triple-transgenic (3xTg), exhibit more significant Aβ deposition and progression of behavioral deficits compared to single APP transgenic mice." (PMID 40744926, 2025). "In this study, we investigated the effects of a specific inhibitor of 37/67kDa LR on APP maturation and Aβ generation in fibroblasts from patients affected by familial Alzheimer’s disease (carrying PSEN2 M239V pathogenic mutation, fAD2, fAD3 or not fAD1), compared with healthy unaffected controls." (PMID 33207563, 2020). "Double transgenic mice APP/PS1 expressing a chimeric mouse/human APP (Mo/HuAPP695swe: APP Swedish mutation) and a mutant human presenilin 1 (PS1-dE9), both directed to central nervous system neurons, have been generated as animal models of familial Alzheimer's disease." (PMID 23205014, 2012).
familial Alzheimer disease (continued). "Here, we performed transcriptomic and functional characterization of iPSC-neurons derived from non-demented control (NDC) donors and from familial Alzheimer’s Disease patient donors harboring an amyloid precursor protein (APP) duplication (APPDup)." (PMID 38167174, 2024). "Humanin was discovered in 2001 as a 24-mer peptide that inhibited neuronal cell death induced by neurotoxic amyloid-β (Aβ) peptides and by mutants of familial Alzheimer’s disease (FAD) genes, i.e., APP amyloid precursor protein (APP), presenilin-1 (PS1), and presenilin-2 (PS2)." (PMID 38132360, 2023).
Anxiety (141 papers, 2012 to 2026). Intense feelings of nervousness, tension, or panic often arise in response to interpersonal stresses. "We previously demonstrated that administration of BCI-838 to a mouse model of brain accumulation of oligomeric AβE22Q (APPE693Q = “Dutch APP”) reduced learning behavior impairment and anxiety, both of which are associated with the phenotype of Dutch APP mice." (PMID 39081972, 2023). "Regarding BPSD, anxiety and depression are the most common in APP mutations, while depression and irritability are more frequent in LOAD." (PMID 36313020, 2022). "Because comorbid anxiety is prevalent among patients with AD, we explored the effects of IH on anxiety‐like behaviors and associated factors in APP/PS1 mice." (PMID 31877583, 2020). "The Arg1 insufficiency in APP mice precipitated more behavior impairment evidenced by more anxiety, more exploratory behavior, and decreased fear associated memory." (PMID 33519806, 2020). "While the APP single knock-in allele is sufficient to cause elevated anxiety-related behavior, the enhanced fear response requires the presence of both APP and PS1 knock-in alleles." (PMID 24278307, 2013). "Together, these findings suggest that the PLCγ2-P522R variant promotes an anxiety phenotype in APP/PS1 mice, which may promote longevity via protection against environmental threats through mechanisms associated with altered microglial functions." (PMID 40038760, 2025). "Our findings from animal models further demonstrate that a malnourished diet contributed to the anxiety‐ and depression‐like behaviors in APP/PS1 mice and was associated with neurotransmitter imbalance and the downregulation of c‐Fos gene expression in the midbrain (VTA) and striatum (putamen)." (PMID 39868480, 2025). "Collectively, we demonstrated that a HS diet could induce neuronal loss, suppress the expression of synaptic proteins, lead to Aβ plaque aggregation in the hippocampus, and cause anxiety-like behavior in APP/PS1 mice." (PMID 39519278, 2024). "We investigated the potential mechanisms that may underlie the reduction of anxiety- and depression-like behaviors in APP/PS1 mice induced by treadmill exercise." (PMID 39744519, 2024). "In summary, we demonstrated that a HS diet could induce neuronal loss, suppress the expression of synaptic proteins, lead to Aβ plaque aggregation in the hippocampus, and cause anxiety-like behavior in APP/PS1 mice." (PMID 39519278, 2024). "To explore whether and how aBLA or pBLA is involved in AD-related anxiety, we first examined Aβ pathologies in the aBLA and pBLA of APP/PS1 mice carrying mutated APP and PS1 genes, overproducing Aβ in the brain." (PMID 31924799, 2020). "Hyperactivity in rTg4510 mice could be associated with anxiety-like behavior as impaired anxiety has been observed in several lines of tau and APP transgenic mice." (PMID 29624602, 2018). "Many APP transgenic models show cognitive decline reminiscent of the human disorder, and several also display non-cognitive symptoms associated with the disease, including anxiety, aggression, locomotor hyperactivity and circadian disturbances." (PMID 22709352, 2012). "Furthermore, a malnourished diet contributed to malnutrition and depression‐ and anxiety‐like behaviors in APP/PS1 mice, which was associated with imbalances in the dopamine and acetylcholine levels and downregulation of the cAMP/c‐Fos signaling pathway in both the midbrain and striatum." (PMID 39868480, 2025). "In conclusion, our study showed that in both patients with AD and APP/PS1 mice, poor baseline nutritional status was associated with subsequent deterioration of NPSs, particularly, depression, apathy, and anxiety, over a follow‐up period." (PMID 39868480, 2025). "The open field test results indicate that Danggui Shaoyao San and its disassembled prescriptions alleviate anxiety-like behavior in APP/PS1 mice to varying extents, with the full-formula group showing the most pronounced effect." (PMID 40822397, 2025).